TLR5 (toll like receptor 5)
Diseases named in the same sentence as TLR5 in open-access papers (continued):
Sharing a sentence is not in itself a finding about the gene and the disease.
atherosclerosis (9 papers, 2012 to 2024). A disease characterized by the build-up of fatty material and calcium deposition in the arterial wall resulting in partial or complete occlusion of the arterial lumen. "Although it remains unclear which ligand is responsible for the observed effect in the current study, we do show the importance of hematopoietic TLR5 deficiency in the early stage of atherosclerosis formation." (PMID 28202909, 2017). "A recent study also reported that TLR5-NADPH oxidase 4 (Nox4) promotes the migration of smooth muscle cells in atherosclerosis and facilitate the formation of atherosclerotic plaque." (PMID 39021802, 2024). "Here, we demonstrate that TLR5-mediated Nox4 activation regulates the migration of SMCs, leading to neointimal plaque formation in atherosclerosis." (PMID 31292433, 2019). "TLR5-Nox4 signaling cascade plays a key role in atherosclerosis, hardening of the arteries, in which fatty deposits known as plaques accumulate in the inner walls of arteries." (PMID 31292433, 2019). "Taken together, these results demonstrate that TLR5-mediated Nox4 activation regulates the migration of SMCs, leading to neointimal plaque formation in atherosclerosis." (PMID 31292433, 2019). "Among our network genes previously associated with arterial aging, TLR5 is a member of the TLR (toll-like receptor) family, which is an established mediator of atherosclerosis due to its role in immune response through the induction of inflammatory cytokines." (PMID 29073909, 2017). "This implicates a pro-atherogenic effect of stimulation of TLR5 on T-cells in a pro-inflammatory environment, like observed in atherosclerosis." (PMID 28202909, 2017). "In conclusion, H2O2 generation through Nox4 activation plays a significant role in mediating flagellin-induced atherosclerosis, and we first verified a link between TLR5 and atherosclerosis." (PMID 27146088, 2016). "Here, we show a molecular link between TLR5 and atherosclerosis through the activation of the Nox isozyme." (PMID 27146088, 2016). "However, the molecular link between TLR5 as a bacterial flagellin receptor and atherosclerosis is still unclear." (PMID 27146088, 2016). "Moreover, we demonstrated that the Nox4-deficient ApoE KO mice exhibited significant protections against rFliC-mediated atherogenesis indicating that TLR5-dependent Nox4 activation is critical for the development of atherosclerosis." (PMID 27146088, 2016). "Targeting the TLR5-Nox4 cascade in endothelial cells could be a possible therapeutic strategy for atherosclerosis." (PMID 27146088, 2016). "Since imbalanced inflammation is key in the development and progression of atherosclerosis, we investigated whether monocytes and T-cells lacking TLR5 differ in migratory and inflammatory behavior and whether hematopoietic TLR5 deficiency influences atherosclerotic plaque formation in vivo." (PMID 28202909, 2017). "Moreover, although baseline TLR5 deficiency was able to attenuate atherosclerotic plaque formation, from a clinical perspective it remains of interest to see whether TLR5 inhibition at a later stage would also be able to reduce or stabilize already manifest atherosclerosis." (PMID 28202909, 2017). "We conclude that TLR5-dependent Nox4 activation and subsequent H2O2 generation play critical roles for the development of atherosclerosis." (PMID 27146088, 2016). "Since evidence for the role of TLR5 is lacking, we aimed to establish this in the immune axis of atherosclerosis." (PMID 28202909, 2017). "We first provided a molecular link between TLR5-mediated H2O2 generation and atherosclerosis." (PMID 27146088, 2016).
atherosclerosis (continued). "To validate the effect of TLR5 on atherosclerosis, we injected rFliC or ΔrFliC, non-functional flagellin, into the ApoE mice with HFD." (PMID 27146088, 2016).
melanoma (9 papers, 2016 to 2024). A malignant, usually aggressive tumor composed of atypical, neoplastic melanocytes. "TLR5 can effectively alleviate the stimulation caused by radiation, and SOX10 independently regulates the expression of IRF1 in melanoma through the JAK-STAT signaling pathway." (PMID 37113996, 2023). "We investigated the effect of combining photodynamic therapy (PDT) and TLR5 agonist flagellin-adjuvanted tumor-specific peptide vaccination (FlaB-Vax) on the promotion of PD-1 blockade-mediated melanoma suppression using a mouse B16-F10 implantation model." (PMID 33171765, 2020). "The successful treatment of bilateral melanoma in mice has been demonstrated through the utilization of a combination of PDT and Toll-Like Receptor 5 (TLR5) agonist flagellin." (PMID 38481994, 2024). "Although TLR5 is not a prognostic marker in melanoma, various studies have shown that TLR5 agonists can lead to synergistic anti-tumor properties with ICIs and other therapies in cancer types, including melanoma." (PMID 37628585, 2023). "In melanoma, TLR5 is not as well studied as TLR2 or TLR4, but evidence suggests that many cell lines express TLR5 to varying degrees, and therefore, innate and adaptive immunity could be activated by TPV/Δ2L/Δ66R/FliC infections in melanoma cells." (PMID 37628585, 2023).
diabetes (8 papers, 2017 to 2024). "Interestingly, analysis of the incidence of older female mice (over 17 weeks of age), revealed that TLR5-deficient NOD mice developed more diabetes than TLR5-sufficient NOD mice at the same age." (PMID 38482010, 2024). "Finally, and unexpectedly, TLR5-deficiency only affected spontaneous diabetes development in older NOD mice." (PMID 38482010, 2024). "We found that TLR5-deficient DCs are hyper cytokine secretors that can modulate antigen-specific CD4+ T cell proliferation, leading to increased diabetes development in older adult mice." (PMID 38482010, 2024). "Animal experiments demonstrated that gavage with Lachnospiraceae accelerated the development of diabetes in obese mice and aggravated the inflammation of intestinal epithelial cells in TLR5−/− mice." (PMID 34020714, 2021). "Gene expression of the plasma membrane localized Tlr5 was significantly decreased compared to their healthy controls 8 weeks after STZ-induced diabetes." (PMID 29538462, 2018). "In the PCC group, there was a correlation between duration of diabetes and neutrophil TLR1 (r = −0.730, p = 0.04), TLR3 (r = 0.766, p = 0.03) and TLR5 (r = 0.843, p = 0.01) mRNAs." (PMID 28794498, 2017). "Interestingly and in contrast to these findings, our results showed a reduced gene expression of Tlr5 and Tlr8 8 weeks after STZ-induced diabetes in the heart." (PMID 29538462, 2018). "This may also suggest that TLR5 has a stronger effect on the progression, rather than the initiation, of diabetes development, which may prove to be important therapeutically." (PMID 38482010, 2024).
Legionnaires' disease (8 papers, 2007 to 2022). A pneumonia caused by Legionella pneumophila and other Legionella species, which is characterized by fever, cough, progressive respiratory distress, and which is often accompanied by extrapulmonary manifestations. "For instance, the common TLR5-392STOP variant in humans is associated with increased susceptibility to Legionnaires’ disease." (PMID 34897511, 2022). "Nonetheless, the dominant loss-of-function polymorphism of TLR5 (TLR5392STOP) is present in a high percentage of population in spite of increased susceptibility to Legionnaire’s disease." (PMID 34395439, 2021). "TLR5 is activated by flagellin protein, and in humans a common polymorphism in the TLR5 gene causes a deficiency in mediating signals from flagellin and increased susceptibility to Legionnaire's disease." (PMID 18034886, 2007). "Other, atypical flagellated respiratory pathogens that affect immunocompromised individuals include pathogens that cause Legionnaire’s disease and melioidosis and it is noteworthy that TLR5 was reported as a risk factor for defining outcome in these infections." (PMID 31133714, 2019).
lung carcinoma (8 papers, 2013 to 2025). "The non-synonymous SNP rs5744174, coding for F616L in TLR5, was associated with overall survival in a group of patients diagnosed with lung cancer of any type (p = 0.0205) and with the survival in NSCLC patients (p = 0.0056)." (PMID 36140341, 2022). "The effects of TLR5 in lung cancer have mostly been associated with anti-tumor activity, with some indications of pro-tumor effects reported in other cancer types." (PMID 36389785, 2022). "Therefore, we assume that rs2072493_N592S variant alter the TLR5 signaling pathway resulting in dysfunctional biological processes which, in the end, culminate with the increased risk of lung cancer development." (PMID 36140341, 2022). "What is most worthy of mention, and had not been investigated before, is the strong effect on the response of lung cancer cell line (H1299) to the combined treatment with frequently used cytostatic drugs and the flagellin, the TLR5 agonist." (PMID 36140341, 2022). "Although TLR7, a sentinel of viral infection, has already been studied in the context of the lung cancer, little is known about the contribution of TLR5 to immune responses in the human lung in this context." (PMID 36140341, 2022). "In A549 lung cancer cells, inhibition of a flagellin-derived agonist delayed tumor growth through the TLR5 and MyD88-dependent pathway and even suppressed cell viability." (PMID 36389785, 2022). "Next, we evaluated the effect of the SNPs on survival of the lung cancer patients in order to obtain a better insight how tested TLR5 SNPs influence the survival rate of the carrier." (PMID 36140341, 2022). "The aim of the genetic association analysis was to investigate the relationship between the frequency of the TLR5 genotypes and the risk for COPD and lung cancer development." (PMID 36140341, 2022). "The aim of this analysis was to also investigate if any of tested SNPs in TLR5 were associated with clinical characteristics in COPD and lung cancer patients." (PMID 36140341, 2022). "Additionally, NME3, identified as a component of this pathway, enhances TLR5-mediated NFκB signaling in response to flagellin, thereby contributing to antitumor immunity in lung cancer patients." (PMID 40841456, 2025). "In lung cancer, TLR5 was correlated with good prognosis, but TLR7 with poor prognosis." (PMID 32174922, 2020). "We incubated HEK-Blue cells expressing human TLR2, TLR3, TLR4, TLR5, TLR7, TLR8, TLR9, or the intracellular PRR protein NOD2 with 100 μg/ml DRibbles derived from the mycoplasma free lung cancer cell line UbiLT3." (PMID 27490927, 2016). "In conclusion, we can say that our results suggest that TLR5 could be potentially considered as a biomarker for COPD and LC development with functional relevance, which is reflected in increased sensitivity to chemotherapeutic drugs frequently applied in lung cancer treatment." (PMID 36140341, 2022).
pneumonia (8 papers, 2010 to 2024). An acute, acute and chronic, or chronic inflammation focally or diffusely affecting the lung parenchyma, caused by an infection in one or both of the lungs (by bacteria, viruses, fungi, or mycoplasma.). "We also demonstrated that TLR5 effectively enhances vaccine efficacy against pneumonia, leading to increased survival rates from pneumococcal infection in old mice." (PMID 38167804, 2024). "Furthermore, the administration of TLR5 agonist (flagellin) enhances the IL-22 production from group 3 ILCs during S. pneumoniae-induced pneumonia." (PMID 32849610, 2020). "Also, the TLR5 agonist (flagellin) administration increases the efficacy of antibiotic treatment during pneumonia." (PMID 32849610, 2020). "We have previously demonstrated that the amino acid polymorphisms TLR5-1205C/T, NLRP3-2906A/G, and NOD2-2197A/C in PRRs in pigs, which have been shown to alter pathogen recognition and cytokine production at the cellular level, are also associated with pneumonia severity in commercial pig farms." (PMID 39202462, 2024). "During pneumonia, AECs recognize various pathogens due to the expression of different PRRs, including TLRs [TLR1, TLR2, TLR4, TLR5, TLR6 (Extracellular TLRs), and TLR3, TLR7, TLR8, and TLR9 (Intracellular TLRs)] and NLRs comprising inflammasome." (PMID 32849610, 2020). "In mice pneumonia studies, TLR2, TLR5 and TLR9 were required for effective innate immune responses against L. pneumophila." (PMID 20615218, 2010).
psoriasis (8 papers, 2015 to 2025). An autoimmune condition characterized by red, well-delineated plaques with silvery scales that are usually on the extensor surfaces and scalp. "Recently, the association of the TLR5 rs5744174 (A > G) polymorphism with the response to biological drugs indicated in moderate-to-severe psoriasis (anti-TNF: n = 376; UTK: n = 230) has been evaluated in patients from Denmark." (PMID 33921427, 2021). "Finally, we conducted a replication analysis for SNPs in the TLR2, TLR5, and ANKRD55 genes, which were previously associated with treatment response to IL-23 inhibitors in a pre-selected SNP association study of a cohort of 18 patients with moderate-to-severe psoriasis from Spain." (PMID 41153410, 2025). "Real-time polymerase chain reaction (PCR) revealed that the expression levels of TLR3, TLR5, TLR6, TLR7, TLR9, and TLR10 in lesional skin were higher than those in peripheral blood mononuclear cells (PBMCs) of the same patients with psoriasis." (PMID 34790055, 2021). "A study conducted on eight samples of normal skin and 15 samples of lesional and non-lesional biopsies from patients with psoriasis demonstrated that TLR1, TLR2, and TLR5 are constitutively expressed in the keratinocytes of normal skin." (PMID 34790055, 2021).
rheumatoid arthritis (8 papers, 2015 to 2025). A chronic, systemic autoimmune disorder characterized by inflammation in the synovial membranes and articular surfaces. "Recently, the involvement of Tlr5 in inflammatory diseases such as rheumatoid arthritis was also discovered." (PMID 33479312, 2021). "Moreover, for TH22/17-associated autoimmune conditions including rheumatoid arthritis, TLR2, TLR4, and TLR5 modulation holds potential for managing these disorders." (PMID 37760825, 2023). "In autoimmune diseases characterized by TH22-/TH17-dominated immune responses, such as rheumatoid arthritis and Arthus reactions, the expression of TLR2, TLR4, and TLR5 is upregulated." (PMID 37760825, 2023).
ulcerative colitis (8 papers, 2012 to 2025). An inflammatory bowel disease involving the mucosal surface of the large intestine and rectum. "firstly found that emodin reduced the expression of TLR5 and MyD88, up-regulated IκB levels, as well as inhibited the nuclear translocation of NF-κB p65 to ameliorate ulcerative colitis symptoms, via suppressing flagellin-TLR5-NF-κB signaling pathway." (PMID 34629100, 2021). "The TLR5 N592S mutation also reportedly affects TNF-a and IFN-r levels in ulcerative colitis patients." (PMID 29179462, 2017).
cystic fibrosis (7 papers, 2009 to 2019). Autosomal recessive disorder caused by pathogenic variants in the CFTR gene (cystic fibrosis transmembrane conductance regulator), which encodes a chloride and bicarbonate channel expressed in epithelial cells, and follow the diagnosis criteria. "At the opposite end, it has been recently reported that the TLR5 mRNA expression is increased in cystic fibrosis airway EC and that, as a probable consequence, these cells almost exclusively rely upon TLR5 to sense P. aeruginosa." (PMID 19806220, 2009). "TLR2 stimulation may alter the expression of TLR5 as expression of TLR5 is upregulated in neutrophils from patients with cystic fibrosis in response to TLR2 stimulation." (PMID 31774834, 2019). "However, TLR5 is the only TLR that is significantly higher expressed on neutrophils in the cystic fibrosis lung." (PMID 21901099, 2011). "We found that, in CF AECs expressing a deletion of a phenylalanine at position 508 of the gene coding for Cystic Fibrosis Transmembrane Conductance Regulator (CFTRdelF508), exposure to live Pseudomonas aeruginosa upregulates IL-33 via the TLR2 and TLR5 signaling pathways." (PMID 26793709, 2015).
malaria (7 papers, 2014 to 2024). Malaria is a serious and sometimes fatal disease caused by a parasite that commonly infects a certain type of mosquito which feeds on humans. "Carriers of the T allele were at higher risk for developing Pv-malaria (TLR5 OR = 2.1, [95% CI: 1.0–4.3, p = 0.034]; TLR9 OR = 1.3, [95% CI: 1.0–1.7, p = 0.02])." (PMID 28850598, 2017). "It needs validation with a larger sample size to confirm the importance of TLR9 and TLR5 in Pv-malaria." (PMID 28850598, 2017). "Association of the polymorphisms TLR5 R392StopCodon and TLR9 -1486C/T with Pv-malaria and the C/C genotype of the SNP TLR9 -1237C/T with increased parasitemia was observed." (PMID 28850598, 2017). "The data presented in this study suggest an association of polymorphisms TLR5 and TLR9 with Pv-malaria." (PMID 28850598, 2017). "TLR5 R392StopCodon and TLR9 -1486C/T may predispose individuals to P. vivax malaria, while TLR9 -1237C/T was associated with Pv-malaria with high parasitemia." (PMID 28850598, 2017). "First line of defense for pathogen recognition arisen with toll-like receptors TLR2, TLR4 and TLR5 in different infectious diseases such as malaria (adj pval 0.014), amoebiasis (adj pval 0.027) and legionellosis (adj pval 0.039) according to GEA over KEGG database." (PMID 29028836, 2017). "Notably, complement genes (C1QA, C1QB, C1QC), apoptotic genes (PDL1, PDL2, APOL1, APOL2, FAS), inflammatory caspases (CASP1, CASP5), TLR pathway genes (TLR1, TLR4, TLR5, TLR8), cytokines (IL6, IL10), and granzyme (GZMB) were among the genes upregulated during symptomatic malaria." (PMID 39161730, 2024).
colon carcinoma (6 papers, 2014 to 2024). "Based on the literature, colon cancer cells highly express TLR5 and can secrete the chemokine IL-8 upon stimulation with flagellin, while B cells express the receptor but cannot secrete this chemokine." (PMID 25538693, 2014). "TLR5 expression in the intestinal epithelium protects against microbial infections, inflammation, tissue injury, radiation colitis, proapoptotic stimuli, and colon cancers." (PMID 35893896, 2022). "Microbial cells and flagellin extracted from fecal samples of 61 healthy donors modulated the viability of the human (HT29) colon carcinoma cells and the host response through the stimulation of the expression of Toll-like receptor 5, lectin RegIIIα and three interleukins (IL-8, IL-22 and IL-23)." (PMID 32144387, 2020). "Armed with a CBLB502 TLR5 agonist, CAR133-NK92 cells were shown to be capable of specifically eliminating CD133-positive colon cancer cells in a CAR133-dependent manner and indirectly eradicating CD133-negative colon cancer cells in a CBLB502-specific endogenous immune response manner." (PMID 37731205, 2023). "Therefore, the antitumor effect of CAR133-i502-NK92 cells in this model should not be affected by the low TLR5 expression on colon cancer cells." (PMID 37731205, 2023).